MTOR (mechanistic target of rapamycin kinase)
Diseases named in the same sentence as MTOR in open-access papers (continued):
Sharing a sentence is not in itself a finding about the gene and the disease.
cancer (continued). "Combined with the results of enrichment, we noticed a set of pathways involve in tumorigenesis and process, including protein metabolic, cell apoptosis, intracellular signal transduction, cell cycle phase transition, stem cell pluripotent regulation, mTOR signaling pathway and pathway in cancer." (PMID 28977866, 2017). "Signaling of mTOR pathway is vital for cancer cell growth and survival in GBM patients." (PMID 28198665, 2017). "Since the anti-cancer efficacy of mTOR inhibitors used as monotherapy was limited in cancer patients, pre-clinical studies have tested therapeutic approaches that combine mTOR inhibitors with other anti-cancer agents." (PMID 29104248, 2017). "AKT/mTOR signaling is activated in many human cancers, including RCC." (PMID 27682873, 2017). "Overall, we can expect that the development of novel mTOR co-targeting strategies may achieve durable responses and cancer remission, hence increasing the life expectancy and quality of life of HNSCC patients." (PMID 28822012, 2017). "Taken together, our and other studies suggest that p-4E-BP1 may be an effective biomarker to predict mTOR inhibitor sensitivity in SCLC as well as in other cancers." (PMID 29290965, 2017). "In this review, we discuss and speculate about the future use of therapies that target mTOR in cancer by focusing mainly on their effects on tumor endothelial cells." (PMID 29104248, 2017). "The mTOR enhances tumorigenesis and has become an attractive therapeutic target in cancer." (PMID 28061838, 2017). "Furthermore, GSK3β has been extensively investigated for its role in cancer progression where it is reported to be under control of several different pathway including PI3K/Akt/mTOR, Ras/Raf/MEK/ERK, Wnt/β-catenin, Hedgehog, and Notch80." (PMID 28484273, 2017). "Additionally, autophagy also has been reported to emerge in irradiated cancer cells via inhibition of mTOR and induction of ER stress and DNA damage; therefore, sensitivity to radiation depends on many complex factors and variables." (PMID 28629173, 2017). "In the present study, we found a specific distribution of p-mTOR in normal and carcinoma tissues." (PMID 28831205, 2017). "In addition, PI3K/AKT/mammalian target of rapamycin (mTOR) signaling has also found to confer resistance to DDP-based treatment in many cancers." (PMID 27014910, 2016). "This clearly indicates the presence of a feedback loop from HIF-1α to mTOR signaling, which may promote cancer cell survival in the hypoxic niche." (PMID 27821815, 2016). "TIF-IA is essential for the initiation of pre-rRNA transcription through its interactions with RNA Pol I and UBF/SL1 at the ribosomal DNA promoter, and it is hyperactivated by various oncogenic signaling pathways, such as ATK, ERK/RSK and mTOR, in human cancer." (PMID 26506235, 2016). "In conclusion, combination of targeting both mTOR and Mnk/eIF4E signaling pathways to enhance effectiveness of mTOR-targeted cancer therapy might be significant innovation for the personalized treatment of NSCLC." (PMID 27050281, 2016). "Recent studies have shown that mTOR inhibition could lead to feedback activation of cytoprotective autophagy, which counteracts the anti-cancer activity by a number of mTOR inhibitors." (PMID 27385099, 2016). "For that reason, several studies are concentrated on understanding the precise role of mTOR in cancer, and uncovering whether mTOR might be an interesting druggable target and under which circumstances." (PMID 27486382, 2016). "Therefore, mTOR pathway has been recognized as an important and attractive therapeutic target for cancer therapy." (PMID 27595116, 2016). "RTK-PI3K-Akt-mTOR signaling cascade is a frequently altered pathway in cancer." (PMID 26918353, 2016). "The mTOR pathway is an important regulator of cell signaling with known roles in physiological processes (including cell growth, survival and autophagy) and in cancer." (PMID 27809291, 2016).
cancer (continued). "In addition, lysosome inhibitory activity of CQ has key roles in PI3K/mTOR inhibitor-resistant cancer cell death." (PMID 26964637, 2016). "Tumor growth driven by hyperactivation of mTOR is widely prevalent in numerous cancer types." (PMID 27826244, 2016). "Besides its role in cancer cell growth and proliferation, the mTOR pathway also plays an important role in cancer formation." (PMID 26775697, 2016). "DEPTOR is an endogenous inhibitor of mTOR complexes, de-regulated in cancers." (PMID 26992219, 2016). "Collectively, the data support a mechanism whereby cancer cells take up and metabolize lactate in the context of bioavailable glutamine in normoxic, but not hypoxic conditions, thereby upregulating mTOR signaling." (PMID 27134166, 2016). "In order to overcome the inferior pharmacokinetic properties of rapamycin and to further explore the therapeutic utility of mTOR inhibition to combat cancer, numerous analogs of rapamycin were subsequently developed based on the structure of rapamycin as a molecular scaffold." (PMID 27826244, 2016). "Additionally, this study provides a mechanistic explanation for the beneficial effects of resveratrol, which is mTOR-dependent autophagy induction and reduction of cancer cell viability." (PMID 26902888, 2016). "The PI3K/AKT/mTOR pathway is crucial for the regulation of chemoresistance in various cancers." (PMID 27293459, 2016). "Interestingly, the inhibition of mTOR by rapamycin in cancer cells was shown to enhance aerobic glycolysis and to decrease uncoupled mitochondrial respiration." (PMID 28033363, 2016). "Many inhibitors of the PI3K/Akt/mTOR pathway have shown activity in preclinical cancer models." (PMID 27821815, 2016). "If this hypothesis is true, it could be possible that cancer with a high PDGFRα amount is characterized by downregulated mTOR signaling." (PMID 27293550, 2016). "Besides, fisetin showed cancer-preventive effects via modulating the PI3K/Akt/mTOR pathway in cancer cell models, and in animal models." (PMID 27529277, 2016). "Curcumin exhibits its anticancer effects against different types of cancer by targeting multiple therapeutically important cancer signaling pathways such as Ras, mTOR (mammalian target of rapamycin), FOXO1 (forkhead box protein 1), Wnt/β-catenin, PI3K (phosphoinosmde-3-kinase) and AKT pathways." (PMID 27738325, 2016). "Literature suggest that PI3K/ AKT/ mTOR pathway proteins are critical for the progession of cancer." (PMID 27380262, 2016). "Inhibition of mTOR, on the other hand, results in cancer cell apoptosis." (PMID 27167344, 2016). "(iii) Extracellular signals, like cytokines and chemokines secreted in the inflammatory microenvironment, can activate the p38 MAPK and Akt/mTOR signaling pathways by binding to a chain of tyrosine kinases, which further stimulate transcription factors, thereby leading to cancer cell survival." (PMID 27507058, 2016). "Phosphorylation of mTOR plays a pivotal role in the proliferation and survival of cancer cells." (PMID 27264609, 2016). "This context dependency of HIFs and mTOR signalling in cancer warrants further study." (PMID 26837714, 2016). "The PI3K/Akt/mTOR pathway plays a key role in the tumorigenesis of many cancers, including HNSCC." (PMID 27764820, 2016). "As lipid synthesis and utilization could be complementary in supporting cancer cell growth, we next examined effect of mTOR-inhibition on lipid catabolism." (PMID 27563814, 2016). "Additionally, an overview on the present status of the use of mTOR inhibitors for cancer and CSCs eradication will be provided." (PMID 27826244, 2016). "The mechanistic target of rapamycin (mTOR) is a rational target for cancer treatment." (PMID 27563814, 2016). "Our data surprisingly indicated that loss of AIM2 in HCC cells contributed to disease progression via mammalian target of rapamycin (mTOR)-S6K1 pathway activation, which may pave a new avenue to treat AIM2 deficient cancer by suppression of mTOR." (PMID 27167192, 2016).
cancer (continued). "Since members of AKT/mTOR/p70S6K pathway is known to be master regulators of aerobic glycolysis in normal tissue as well as in cancer cells, we wanted to test whether the two inhibitors had any effect on metabolism." (PMID 26771843, 2016). "In addition, several studies have suggested that mTOR inhibitor can enhance the efficacy of different chemotherapeutic agents in various cancers." (PMID 26909611, 2016). "Importantly, the PI3K-Akt-mTOR pathway plays a central role in cancer cell growth, proliferation, and survival, and is overexpressed in numerous cancers including breast, ovarian, and pancreatic." (PMID 27589846, 2016). "The PI3K/ Akt/mTOR signaling pathway is aberrantly activated in many cancer types." (PMID 27007154, 2016). "With the discovery of rapamycin, the race began to create a mTOR inhibitor for cancer treatment." (PMID 26962408, 2016). "TKI resistance can arise through aberrant activation of the PI3K/AKT/mTOR axis in several cancer types, including NSCLC, often through PTEN deletion or activating PIK3CA mutations; however, such mechanisms were elucidated primarily in the context of EGFR inhibitors." (PMID 27472392, 2016). "Gene expression was compared across H460, A549 and H1975 cells using two gene expression arrays (SABiosciences): one which profiles the expression of genes related to mTOR signalling, and one which profiles the expression of genes related to cancer drug resistance." (PMID 27765909, 2016). "If results translate beyond in vitro cell culture, this finding has implications for the design of treatment strategies in HER2+ cancers, as multiple PI3K/AKT/MTOR inhibitors are being tested in HER2+ cancers, and MEK inhibitors are being tested in a variety of other tumor types." (PMID 27035903, 2016). "They further provide a rationale to combine CAIX and mTOR inhibitors in cancer therapy." (PMID 27153561, 2016). "The mTOR signaling pathway has emerged as an attractive therapeutic target for cancer therapy." (PMID 27031247, 2016). "In addition, the oral pain can limit administration of chemotherapy and mTOR inhibitors, resulting in delivery of suboptimal cancer treatment dosing." (PMID 27334013, 2016). "The mTOR signaling pathway has become a compelling target for cancer treatment." (PMID 26872016, 2016). "Importantly, the PI3K/AKT/mTOR pathway is activated in some cancer stem cells and is crucial for cancer stem cell maintenance." (PMID 27120806, 2016). "The PI3K/Akt/mTOR pathway is a survival pathway that is activated in many types of cancer." (PMID 27252813, 2016). "Allosteric mTOR inhibitors such as Rapamycin derivatives or rapalogs are approved for clinical use in limited cancer types, while a variety of less selective ATP-competitive mTOR, PI3K or AKT or duel mTOR/PI3K multikinase inhibitors are still in clinical development." (PMID 27351224, 2016). "mTOR is emerged as a critical effector in cell-signaling pathways commonly deregulated in human cancers suggesting that mTOR inhibitors may be useful in oncology." (PMID 27713912, 2016). "Growth-promoting pathways, such as the mTOR pathway, are involved in both cancer and aging." (PMID 27155197, 2016). "Several clinical trials of mTOR targeted-therapeutic are currently underway in cancer clinics." (PMID 27911920, 2016). "However, AMPK acts opposite to Akt, and is a negative regulator of the mTOR pathway, which has been correlated with tumor suppression and better prognosis in cancer patients." (PMID 27285995, 2016). "Re-activation of mTOR signalling has been described as a mechanism potentially contributing to the development of resistance to various TKIs in cancer cells but the downstream mechanisms by which it does so have been largely unknown." (PMID 27402251, 2016).
cancer (continued). "Pre-transplant risk factors for de novo cancer have not been well described before while post-transplant risk factors for de novo cancer such as ATG induction, mTOR inhibitors, rejection and EBV status are already known and have been described in several previous publications." (PMID 27398803, 2016). "Pan-mTOR inhibitors have been developed as cytostatics to inhibit cancer cell proliferation." (PMID 28077803, 2016). "Besides, PI3K and mTOR inhibitors are being developed for the treatment of some types of cancer, due to their apoptotic and antiproliferative effects." (PMID 27142962, 2016). "The PI-3K/mTOR dual inhibitors hold a promise for treating cancers." (PMID 26814436, 2016). "These cancers are sensitive to dual PI3K/mTOR inhibition indicating dependence on the PI3K pathway." (PMID 26863299, 2016). "Our own results suggest that decreased KDM4A expression could contribute to mTOR activation during cancer development, suggesting that this demethylase could act as a context-dependent oncogene." (PMID 27624942, 2016). "Additionally, we found that resveratrol induces death of the cancer cells known to be sensitive to mTOR inhibition in ULK1 dependent manner." (PMID 26902888, 2016). "The development of inhibitors to specifically target the PI3K/Akt/mTOR pathway may also represent a strategy for the prevention and treatment of cancer." (PMID 28036019, 2016). "A more recent cohort of 7,217 patients, transplanted in Italy during 1997–2009, however, also observed a significantly reduced risk (46%) for de novo cancer with use of mTOR inhibitor therapy compared to no mTOR inhibitors." (PMID 27807479, 2016). "PI3K/AKT/mTOR is one of the most frequently deregulated cell survival pathways in cancer." (PMID 27693556, 2016). "The mTOR pathway is deregulated and activated in several types of cancer, significantly contributing to the enhancement of proliferation and the inhibition of autophagy; overexpression of downstream mTOR effectors 4E-BP1, S6K and eIF4E4 leads to poor cancer prognosis." (PMID 26821053, 2016). "We hypothesized that combining vorinostat and sirolimus would increase the sensitivity of cancer cells to these drugs by simultaneously inhibiting mTOR, AKT, and HDAC." (PMID 27589687, 2016). "Synergistic effects mediated by inhibiting both the PI3K and the MAPK pathways have been reported for several types of cancers, and activation of the RAS/MAPK pathway may be associated with the synergistic effects of the PI3K/mTOR- and MEK-pathway inhibitors." (PMID 27102436, 2016). "Furthermore, the current study first established a CXCL12-CXCR7-mTOR cascade, although the mTOR regulation of cancer cell invasion was recently shown." (PMID 27542220, 2016). "Silencing mTOR with siRNA decreased PKM2 protein levels in various cancer cell lines." (PMID 27492148, 2016). "Alteration of mTOR signaling networks, which is a common phenomenon in human cancers, may result from impairment of upstream regulatory mechanisms." (PMID 26623720, 2016). "The approach to RCC treatment has dramatically changed after the appearance of targeted cancer therapy such as multikinase inhibitors, and several treatment options such as with mammalian target of rapamycin (mTOR) inhibitor have been developed for advanced RCC." (PMID 27123976, 2016). "Thus, inhibiting mTOR signaling has become a viable and attractive option for molecular-targeted therapy in human cancers." (PMID 27358039, 2016). "In addition, several studies have demonstrated that both apoptosis and autophagy can be simultaneously induced by mTOR inhibition, to further enhance radiosensitivity in cancer cells." (PMID 27031247, 2016). "Taken together, our findings suggest that NHPI may be developed as a promising candidate for cancer therapeutics by targeting mTOR signaling pathway." (PMID 26940018, 2016).
cancer (continued). "Previous studies have shown that deregulation of the PI3K-Akt-mTOR signaling pathway contributes to numerous hallmarks of tumor progression, like tumor-angiogenesis, cell proliferation, survival and migration in various cancers." (PMID 26967567, 2016). "However, in clinical trials, objective response rate with mTOR inhibitor monotherapy in most cancer types was modest." (PMID 27274989, 2016). "Malignant tumors of breast, ovaries, kidneys, large intestine, head, or neck are characterized by a constant, constitutive expression of mTOR kinase caused by a continuous stimulation of its activation pathway PI3 K/AKT/mTOR or mutations within coding genes." (PMID 27160935, 2016). "Interestingly, the oncogenicity of GOLPH3 seems to be mediated by a mechanism that involves enhanced signaling through the mammalian target of rapamycin (mTOR), conferring cancer cells hypersensitivity to rapamycin." (PMID 27123979, 2016). "In addition, we showed that TRIM44 overexpression leads to high mTOR activity, a finding supported by the reduced mTOR signaling in cancer cell lines after siRNA knockdown of TRIM44, and colocalization of TRIM44 with p-mTOR in patient samples." (PMID 27058415, 2016). "Our findings suggest that NHPI may be developed as a promising candidate for cancer therapeutics by targeting mTOR signaling pathway and as such warrants further exploration." (PMID 26940018, 2016). "The phosphatidylinositol 3-kinase/protein kinase B/mammalian target of rapamycin (PI3K/Akt/mTOR) pathway is known to be frequently activated in several types of cancer and is essential for cancer cell survival, proliferation, angiogenesis, and resistance to chemotherapy." (PMID 28005970, 2016). "At least three types of FDA-approved anti-cancer agent were found to also suppress rRNA synthesis: (i) Temsirolimnus/everolimus (mTOR inhibitors) inhibit RNA Pol I transcription, (ii) topotecan/irinotecan modulate early rRNA processing, and (iii) 5-fluorouracil (5-FU) impairs late rRNA processing." (PMID 26506235, 2016). "Therefore nd inhibition of mTOR signaling as a radiosensitizing strategy in cancer cells has been investigated." (PMID 27031247, 2016). "Thus far, the mTOR modulating actions of these inhibitors as monotherapy in cancer have only achieved modest effects as most agents only resulted in stable disease rather than objective response which is typified by tumor regression in most cancers." (PMID 27826244, 2016). "The PI3K/AKT/mTOR pathway is one of major signal transduction pathways responsible for regulating cell growth, proliferation, survival, apoptosis, and malignant transformation and is frequently hyperactivated in most cancers." (PMID 27293469, 2016). "While clinical use of mTORC1 inhibitor rapalog therapy (e.g. temsirolimus, everolimus) validated mTOR as a cancer target, the effectiveness of these drugs may be limited due to resistance to mTORC2." (PMID 27015560, 2016). "Our results are consistent with recent findings showing that autophagy inhibition in combination with mTOR blockage could lead to a profound anti-cancer activity." (PMID 27385099, 2016). "However, in the course of time, cancers adapt to mTOR inhibition and develop resistance mechanisms that are responsible for the limited efficacy of mTOR inhibitors." (PMID 27153561, 2016). "The cellular signaling pathways for each group of genes under MPS1 inhibition, and the top canonical pathways found included: PI3/AKT signaling, Neurogulin signaling, ErbB signaling, GBM signaling, UVB induced MAPK signaling, mTOR signaling and Molecular mechanism of cancer." (PMID 25991676, 2016). "This flavonoid was found to inhibit mammalian target of rapamycin (mTOR) activity which gets hyperactivated during cancer and controls essential cell growth pathways, autophagy and biosynthesis of proteins, and interfere with the activation ofPI3K/Akt signaling pathway." (PMID 26797598, 2016).